RPL32 (ribosomal protein L32)
Description:
Component of the large ribosomal subunit. The ribosome is a large ribonucleoprotein complex responsible for the synthesis of proteins in the cell.
Synonyms: PP9932; L32; eL32
Tractability: Small molecule: an approved drug acts on it; a structure with a bound ligand is known; a high-quality ligand is known. PROTAC: UniProt records ubiquitination sites on it; ubiquitination databases record sites on it; its protein half-life has been measured; a small molecule that binds it is known. Other modalities: a drug acting on it is in phase 2 or 3 trials.
Gene: Protein-coding gene on chromosome 3 (12,834,485 to 12,841,582, reverse strand). Ensembl gene ENSG00000144713.
Subcellular location: Cytoplasm
Subcellular location (Human Protein Atlas): Cytosol; Endoplasmic reticulum
Pathways (Reactome):
Metabolism of proteins: Eukaryotic Translation Termination; Formation of a pool of free 40S subunits; GTP hydrolysis and joining of the 60S ribosomal subunit; L13a-mediated translational silencing of Ceruloplasmin expression; PELO:HBS1L and ABCE1 dissociate a ribosome on a non-stop mRNA; Peptide chain elongation; Ribosome Quality Control (RQC) complex extracts and degrades nascent peptide; SRP-dependent cotranslational protein targeting to membrane; ZNF598 and the Ribosome-associated Quality Trigger (RQT) complex dissociate a ribosome stalled on a no-go mRNA
Metabolism of RNA: Major pathway of rRNA processing in the nucleolus and cytosol; Nonsense Mediated Decay (NMD) enhanced by the Exon Junction Complex (EJC); Nonsense Mediated Decay (NMD) independent of the Exon Junction Complex (EJC)
Cellular responses to stimuli: Response of EIF2AK4 (GCN2) to amino acid deficiency
Developmental Biology: Regulation of expression of SLITs and ROBOs
Disease: Viral mRNA Translation
Metabolism: Selenocysteine synthesis
Gene Ontology:
Molecular function: RNA binding; structural constituent of ribosome
Biological process: cytoplasmic translation; negative regulation of myoblast fusion; spermatogenesis; striated muscle contraction; translation
Cellular component: cytoplasm; cytosolic large ribosomal subunit; cytosolic ribosome; membrane; cytosol; ribosome; synapse
Genetic constraint (gnomAD): Loss-of-function variants: 0 observed, 12.32 expected, observed/expected ratio (o/e) 0, 90% interval 0 to 0.24. The upper end of that interval is the gene's LOEUF score, 0.24, which puts it in group 1 of 6, group 1 being the genes least tolerant of losing a copy. Missense variants: 117 observed, 168.65 expected, observed/expected ratio (o/e) 0.69, 90% interval 0.6 to 0.81. Synonymous variants: 61 observed, 58.88 expected, observed/expected ratio (o/e) 1.04, 90% interval 0.84 to 1.28.
Homologues: Orthologues: chimpanzee RPL32 (100% identical), dog RPL32 (100% identical), guinea pig RPL32 (100% identical), macaque RPL32 (100% identical), mouse Rpl32 (100% identical), pig RPL32 (100% identical), rat Rpl32 (100% identical), tropical clawed frog XB972976 (93% identical), Caenorhabditis elegans rpl-32 (57% identical). Paralogues in human: POLR2L (13% identical).
Diseases named in the same sentence as RPL32 in open-access papers:
RPL32 is named in the same sentence as 31 diseases in open-access papers, as found by Europe PMC text mining. Sharing a sentence is not in itself a finding about the gene and the disease. The quoted sentences say what the papers report.
breast carcinoma (6 papers, 2017 to 2023). "Functional investigation demonstrated that the loss of RPL32 leads to reduced breast cancer cell viability and migration." (PMID 37017565, 2023). "In breast cancer patients, RPL32 expression is higher in circulating tumor cell clusters with greater metastatic potential than in single circulating tumor cells." (PMID 37017565, 2023). "RPL32 knockdown suppressed the migration and invasion of breast cancer cells in vitro and in vivo in a mouse model." (PMID 33435254, 2021). "In addition, silencing of RPL32 significantly reduces cell migration and invasion in breast cancer cells." (PMID 37017565, 2023). "RPL32 expression was upregulated in breast cancer patient samples and cell lines." (PMID 37017565, 2023). "RPL32 is also found to be up-regulated in human breast cancer tissues and cells." (PMID 34873618, 2021). "Therefore, this study revealed that RPL32 has a potential oncogenic role, indicating that it may be a potential target for molecular targeted therapy in breast cancer treatment." (PMID 33435254, 2021). "The knockdown of RPL32 by a lentivirus-delivered siRNA has a negative effect on the migration and invasion of breast cancer cells in vitro and in vivo." (PMID 34873618, 2021). "Unlike KLK3, RPL32 is also expressed in mice, so a test was performed to confirm there was no detection of mouse cells with these primers and amplification conditions using mouse mammary cell line 4T1 and human breast cancer cell line MDA-MB-231." (PMID 34206049, 2021).
colon cancer (5 papers, 2009 to 2023). "The expression of GAPDH and RPL32 genes, the two well-known reference genes in the literature, was analyzed in the colon cancer cells after treatment with various concentration of glandless kernel extract." (PMID 35058516, 2022). "The equivalence of RPL32 and KRT20 as well as the downstream relation of TFDP1 and DHX32 to these two genes is a first step toward refining the architecture of the colon cancer invasiveness network." (PMID 19180177, 2009). "The large standard deviations and high expression levels of GAPDH and RPL32 mRNAs made them not good internal references for qPCR assays in the human colon cancer cells." (PMID 37705049, 2023). "Glyceraldehyde 3 phosphate dehydrogenase (Gapdh) and ribosome protein L32 (Rpl32) mRNAs, two widely used references in mammalian cells, were not good qPCR references for colon cancer cells." (PMID 36364387, 2022). "These expression differences among them make Bcl2 rather than Gapdh or Rpl32 a preferable qPCR reference for colon cancer cells." (PMID 36364387, 2022). "Glyceraldehyde 3 phosphate dehydrogenase (Gapdh) and ribosome protein L32 (Rpl32) mRNAs were not good qPCR references for the colon cancer cells." (PMID 36364387, 2022). "We also confirmed that GAPDH and RPL32 mRNAs were not good qPCR assay references for the colon cancer cells since they were most abundant mRNAs with large variations under the cell culture conditions." (PMID 35058516, 2022). "The large standard deviations and high expression levels of GAPDH and RPL32 mRNAs suggest that they were not good internal reference genes for qPCR assays in the human colon cancer cell." (PMID 33723275, 2021). "Our results showed that GAPDH and RPL32 (60S ribosomal protein 32) mRNAs were not good qPCR assay references for the colon cancer cells since they were most abundant mRNAs with large variations under the cell culture conditions." (PMID 33723275, 2021). "GAPDH and RPL32 mRNAs were not good qPCR references for the colon cancer cells." (PMID 33723275, 2021).
lung carcinoma (4 papers, 2023 to 2024). "RPL32 overexpression is associated with poor prognosis in patients with lung cancer." (PMID 39199272, 2024). "One study examined whether RPL32 was associated with cisplatin sensitivity in the lung cancer cell lines A549, NCI‐H460, and H1299 and showed that knockout of RPL32 significantly increased cisplatin sensitivity in A549 and NCI‐H460 cells." (PMID 37017565, 2023). "Additionally, silencing RPL32 blocks the cell cycle in lung cancer cells." (PMID 37017565, 2023).
colorectal cancer (2 papers, 2009 to 2024). A primary or metastatic malignant neoplasm that affects the colon or rectum. "KRT20 has historically served as a diagnostic marker for colorectal carcinoma, whereas high expression of ribosomal protein L32, glutaminase, and DEAD/H box polypeptides has been associated with various cancers and metastatic lesions." (PMID 19180177, 2009). "In the context of gastric cancer, RPL15, RPL6 and RPS13 exhibited upregulated expressions, while in colorectal cancer, RPS18, RPS23, RPL28 and RPL32 were found to be downregulated, implicating these ribosomal proteins as potential diagnostic markers for gastric and colorectal cancers, respectively." (PMID 39684863, 2024).
hepatocellular carcinoma (2 papers, 2023 to 2024). A malignant tumor that arises from hepatocytes. "Ribosomal protein L32 (RPL32) can be used as a prognostic biomarker for patients with hepatocellular carcinoma." (PMID 37017565, 2023).
infarction (2 papers, 2010 to 2021). A localised pathological necrosis of tissue resulting from obstruction of the blood supply usually by a thrombus, an embolus, or vascular torsion. "The most stable reference genes were Rpl32, Gapdh and Polr2a in mouse post-infarction heart failure, Polr2a, Rpl32 and Tbp in rat post-infarction heart failure and Rpl32 and Pgk1 in human heart failure (ischemic disease and cardiomyopathy)." (PMID 20331858, 2010). "In the set of tested reference genes, the most stable reference genes were Rpl32, Gapdh and Polr2a in mouse post-infarction heart failure, Polr2a, Rpl32 and Tbp in rat post-infarction heart failure and Rpl32 and Pgk1 in human heart failure (ischemic disease and cardiomyopathy)." (PMID 20331858, 2010).
osteosarcoma (2 papers, 2009 to 2021). A usually aggressive malignant bone-forming mesenchymal neoplasm, predominantly affecting adolescents and young adults. "Furthermore, IACS-010759 upregulates the expression of ribosomal protein genes such as RSP27, RPL11, RPL32, RPL35A, and RPL11, mutations which are found in osteosarcoma-prone Diamond-Blackfan anemia (DBA) patients." (PMID 34965247, 2021).
prostate carcinoma (2 papers, 2009 to 2023). A carcinoma that arises from epithelial cells of the prostate gland. "The expression level of RPL32 in late androgen‐independent cells was significantly higher than that in early androgen‐sensitive cells, suggesting that RPL32 may be positively correlated with the progression of prostate cancer." (PMID 37017565, 2023).
schizophrenia (2 papers, 2013 to 2015). A major psychotic disorder characterized by abnormalities in the perception or expression of reality. "This analysis demonstrated that the levels of eIF2α, RPL13, RPL13A, RPL18A, RPL27A and RPL32 were reduced in schizophrenia patient-derived cells in comparison with controls." (PMID 26485547, 2015).
breast tumors (1 paper, 2006). "An investigation of different housekeeping genes revealed two independent genes, PMM1 and RPL32, suitable for mRNA expression level determination in human breast tumors." (PMID 17054774, 2006).
chronic myeloid leukemia (1 paper, 2023). "Previous evidences illustrate that RPL32 plays an important role in the SF3B1 mutation for chronic myeloid leukemia (CML) disease progression, CD52 helps identify molecular signature of CML and NFKBIA plays a strategic role in CML molecular response." (PMID 38096269, 2023).
interstitial lung disease (1 paper, 2008). A diverse group of lung diseases that affect the lung parenchyma. "PSMB2 and RPL32 are, therefore, suitable reference genes to normalize qRT-PCR in BAL cells in sarcoidosis, and other interstitial lung disease." (PMID 18671841, 2008). "We, therefore, recommend PSMB2 and RPL32 as suitable reference genes for the normalisation of the gene expression in unseparated BAL cells, namely in interstitial lung diseases." (PMID 18671841, 2008). "We, therefore, suggest that the use of single reference genes PSMB2 or RPL32 is sufficient for normalisation of target gene expression in BAL cells, at least in interstitial lung diseases, where we validated their expression stability in the second, independent BAL cohort." (PMID 18671841, 2008).
pulmonary hypertension (1 paper, 2022). Increased pressure within the pulmonary circulation due to lung or heart disorder. "To further investigate the relationships among the SRP-DGs and risk of SSc-PH, we constructed a nomogram model using seven SRP-DGs (RPL32, RPS12, RPS14, RPS23, RPS3, RPS7, and SRP9) to predict the risk of pulmonary hypertension complications in patients with SSc." (PMID 36518216, 2022).
sarcoidosis (1 paper, 2008). Sarcoidosis is a multisystemic disorder of unknown cause characterized by the formation of immune granulomas in involved organs. "Finally, to demonstrate effect of traditional (ACTB/GAPDH) and novel (PSMB2/RPL32) reference genes as denominators, expression of two cytokines known associated with sarcoidosis was investigated in sarcoid BAL cells." (PMID 18671841, 2008). "The stability of mRNA expression of PSMB2 and RPL32 genes was further validated in the second, independent BAL cohort of sixty-three sarcoidosis patients and seventeen control subjects." (PMID 18671841, 2008). "Using genes PSMB2 (1.95 ± 1.66; p = 0.02) and gene RPL32 (1.77 ± 1.25; p = 0.03), and gene pair PSMB2-RPL32 (1.65 ± 1.17; p = 0.02) as denominators, CCL2 mRNA levels differed between chest radiographic stage 2 and stage 1 sarcoidosis patients." (PMID 18671841, 2008). "Relative mRNA expression levels of INFG were higher in sarcoidosis patients than in control subjects when the normalisation was done with gene PSMB2 (fold change ± SD: 2.56 ± 1.62; p = 0.004), with gene RPL32 (2.58 ± 1.46; p = 0.004), and with gene pair PSMB2-RPL32 (2.44 ± 1.20; p = 0.02)." (PMID 18671841, 2008).
soft tissue sarcoma (1 paper, 2017). A malignant neoplasm arising from muscle tissue, adipose tissue, blood vessels, fibrous tissue, or other supportive tissues excluding the bones. "Reference genes stably expressed in canine soft tissue sarcoma are β-Glucuronidase (GUSB) and proteasome subunit, beta type, 6 (PSMB6); while in canine mammary gland tumors were a combination of hypoxanthine-phosphoribosyl transferase, ATP-synthase subunit 5B, ribosomal protein L32 and ubiquitin." (PMID 29178874, 2017).
viral infection (1 paper, 2020). "Although our study showed that rpl32 displayed stable expression in A. mellifera under dsRNA treatment, it exhibited the worst stability during IAPV and CBPV infection in A. mellifera, while rps18 was the better reference gene in A. mellifera under dsRNA treatment or viral infection." (PMID 32849362, 2020).
cancer (10 papers, 2008 to 2025). A tumor composed of atypical neoplastic, often pleomorphic cells that invade other tissues. "This may be one of the mechanisms by which RPL32 plays different roles in the proliferation of different cancer cells." (PMID 37017565, 2023). "To evaluate the expression pattern of RPL32 in a pan‐cancer manner, we performed bioinformatics analysis on TNMplot, TIMER, and GTEx (coupled with TCGA) databases, and found that RPL32 was highly expressed in a large proportion of cancers, indicating RPL32 is an oncogene." (PMID 37017565, 2023). "Moreover, based on our data, PSMB2 and RPL32 represent promising candidate reference genes for other lung pathologies such as COPD and cancer." (PMID 18671841, 2008). "A small number of hypoxia-associated genes (APLN, HIF1A, and BNIP3), cancer stem cell (CSC) markers (CD24 and CD44), hormonal regulation (HR) genes (ESR1, PGR, and TFF1), other selected genes (PPARGC1A, ILK), and HKGs (RPL32, GUSB, TBP, OAZ1 and NONO) were also included in the panel." (PMID 34206049, 2021). "Although the other five genes RPL32, TMEM59L, LOC642929, LHX2, and TLCD3B have not been identified in clinical studies indicating their effect on cancers, they may be considered candidate oncogenes because of their high ranking in our constructed gene network modules." (PMID 33708239, 2021). "Interestingly, we observed that GAPDH, GUSB, IPO8, RPL13, RPL32, and UBC genes, as well as RPLP0 + TBP, RPL13 + RPL32, RPL13 + RPLP0, and ACTB + TBP RG pairs, were the only assays whose expression did not depend (P > 0.05) on cancer progression." (PMID 25225161, 2014).
infection (7 papers, 2009 to 2025). The state of being infected such as from the introduction of a foreign agent such as serum, vaccine, antigenic substance or organism. "The viral load was measured 15 days post infection by quantitative RT-PCR relative to a Drosophila reference gene (RpL32)." (PMID 31038124, 2019). "The relative gene expression level of upd3 over RpL32 indicates that upd3 expression after oral infection in haemocytes was much weaker as compared to septic injury with Ecc15." (PMID 27231872, 2016). "This higher-titer infection was also observed by utilizing qPCR on whole transgenic female flies overexpressing WD0830 compared to control flies (wsp/rpl32; t = 2.65, df =6; P = 0.038)." (PMID 27381293, 2016). "DNA was isolated from living flies at 1, 3, 5 and 7 days post-infection and the levels of CaACT1 DNA were quantified using qPCR and the values were normalized to the levels of Drosophila RpL32 DNA." (PMID 22110651, 2011). "The relative inefficient translation of rpL32 mRNA in Drosha knockdown cells could have reflected the requirement for one or more miRs for efficient basal translation of TOP mRNAs, or alternatively, a side effect of the infection by the respective lentivirus." (PMID 25338081, 2014).
tumor (5 papers, 2023 to 2026). "In this study, abnormal expression of RPL32 in HCC was found to be closely related to tumor progression." (PMID 37017565, 2023).
RPL32 also shares sentences with these, for which no sentence is quoted: bacterial infections (1 paper); cardiomyopathy (1); chronic obstructive pulmonary disease (1); cyst (1); Diamond-Blackfan anemia (1); heart failure (1); ischemic disease (1); leukemia (1); lung diseases (1); meningioma (1); pulmonary sarcoidosis (1); retinitis pigmentosa (1).